TOP2A (DNA topoisomerase II alpha)
Diseases named in the same sentence as TOP2A in open-access papers (continued):
Sharing a sentence is not in itself a finding about the gene and the disease.
tumor (continued). "Our findings provide initial evidence that TOP2A may serve as a clinically relevant biomarker in this rare tumor type, with potential utility as both a molecular classifier and a tool for risk stratification in future SCCE management." (PMID 40765849, 2025). "At the mechanistic level, TOP2A can control tumor cell growth via AKT/mTOR pathway modulation." (PMID 38445610, 2024). "In addition, we investigated the correlation between the transcriptional level of TOP2A and tumor stage using TCGA database and reached a consistent conclusion." (PMID 38806610, 2024). "In addition, we examined the effect of knockdown of TOP2A on the tumor growth of C33a cells overexpressing HPV16 E6." (PMID 38205938, 2024). "A comprehensive gene expression analysis of EOC samples from 62 patients (mostly of the high-grade serous histotype) identified a distinct pattern of TOP2A mRNA and protein levels in both tumor epithelial and adjacent stromal cells, which change in response to platinum-based chemotherapy." (PMID 39727717, 2024). "Interestingly, half of the genes analyzed, namely, BIRC5, TOP2A, PLK1, and RRM2, were associated with lung-specific neoplasms." (PMID 39596028, 2024). "We first compared the expression differences of MAPT, WDR62, PLK1, CDCA8 and TOP2A in normal hepatocyte tissues and HCC tissues by TCGA database, and the results showed that the expression levels of MAPT, WDR62, PLK1, CDCA8 and TOP2A were significantly higher in tumour cells than in normal tissues." (PMID 39072983, 2024). "Preclinical models and early clinical trials have demonstrated the efficacy of TOP2A inhibitors, either as monotherapy or in combination with other chemotherapeutic agents, in reducing tumor burden and improving patient outcomes, especially in platinum-sensitive recurrent disease." (PMID 39727717, 2024). "However, overexpression of TOP2A promoted cell proliferation, migration, invasion in vitro and tumor growth in vivo and inhibited apoptosis in HPV16‐positive CC cells with knockdown of HPV16 E6." (PMID 38205938, 2024). "In addition, it was found by tumor cell killing assay that the knockdown of TOP2A significantly downregulated the viability of LUAD cells." (PMID 38374109, 2024). "Although a preliminary association between TOP2A and the incidence or progression of NSCLC has been demonstrated, the precise mechanism by which TOP2A promotes tumor metastasis in NSCLC remains unclear." (PMID 38806610, 2024). "TOP2A levels were closely relevant to tumor size and tumor TNM stages." (PMID 38561479, 2024). "We further examined whether HPV16 E6 affects tumor growth of CC cells in vivo by upregulating TOP2A." (PMID 38205938, 2024). "Moreover, TOP2A is more highly expressed in EZH2-high tumor tissues than in EZH2-low tumor tissues and normal tissues, and the coordinated expression of EZH2 and TOP2A is associated with a worse prognosis in HCC." (PMID 38008711, 2023). "Overall, our study found that TOP2A overexpression may lead to immune escape and immunotherapy failure, resulting in tumor progression and poor overall prognosis of LIHC." (PMID 37980167, 2023). "TOP2A is a promising tumor marker for clinical applications." (PMID 37818158, 2023). "DNA Topoisomerase II Alpha (TOP2A) labelling is associated with a shorter overall and progression free survival, whilst N-MYC downstream- regulated gene 2 (NDRG2) is established as a marker of tumour aggression." (PMID 37860270, 2023). "Notably, TOP2A vaccination significantly decreased tumor volumes as compared to CpG-only treated control mice (p < 0.05)." (PMID 37880313, 2023). "qRT-PCR assay illustrated that TOP2A displayed the highest expression in LIHC bone metastasis lesions, followed by LIHC tumor tissues, while the expression level was the lowest in normal liver specimens, indicating that TOP2A was involved in the LIHC bone metastasis." (PMID 37980167, 2023). "Reduced tumor expression of TOP2A protein was also observed." (PMID 37781045, 2023).
tumor (continued). "Moreover, expression of EZH2 and TOP2A is significantly correlated with tumor differentiation grade, tumor invasion, and TNM stage in HCC." (PMID 38008711, 2023). "Collectively, these results indicate that TOP2A expression may be related to tumor immune tolerance in LIHC and plays a crucial role in tumor immunotherapy and prognosis." (PMID 37980167, 2023). "TOP2A vaccine also reduced tumor weight by nearly 40% (p < 0.05)." (PMID 37880313, 2023). "TOP2A is highly expressed during tumor development and responds to drug therapy for CRC." (PMID 36900162, 2023). "Functional assays confirmed that TOP2A could promote bone-specific metastatic potential and tumor-induced osteolysis in LIHC." (PMID 37980167, 2023). "In addition, similar to our in vitro findings, si-cDCBLD2 treatment in the PDX model resulted in decreased cDCBLD2, increased miR-345-5p, and decreased TOP2A mRNA expression levels in the tumor." (PMID 37781045, 2023). "We then performed hematoxylin and eosin (H&E), Ki67, TOP2A and SA-β-gal staining of tumor tissues." (PMID 38008711, 2023). "In conclusion, this study provides important new insights into the biology of triple negative PABC and suggests that several copy number alterations, particularly 8p loss, TOP2A loss, ESR1 loss and CCNE1 gain are implicated in tumor progression during pregnancy." (PMID 35792986, 2022). "Additionally, they showed that blocking TOP2A prevented tumor development and metastasis in vivo as well as in vitro migration and invasion of HCC cells." (PMID 36672564, 2022). "Besides, it has been reported that TOP2A participates in the regulation of tumor progression by interacting with other genes such as MDM4 and CENPF11,12." (PMID 35778520, 2022). "To investigate the subtypes of monocytes and macrophages that are associated with tumor-related responses, we identified monocytes and macrophages with high expression of cell cycle markers MKI67 and TOP2A, indicating a cluster of proliferating myeloid cells that we termed MKI67+ myeloid cells." (PMID 35013146, 2022). "Furthermore, UALCAN was used to validate TOP2A differential mRNA expression analysis in tumor and normal tissues, and showed TOP2A was overexpressed in LUAD." (PMID 35251970, 2022). "Topoisomerase IIα (TOP2A) plays an oncogenic role in multiple tumor types." (PMID 35778520, 2022). "Furthermore, the CCLE database was used to assess TOP2A expression in a variety of tumor cell lines, and the expression level of TOP2A in MB ranked second among these tumor cell lines." (PMID 35912241, 2022). "Pro-tumorigenic tumors displayed upregulation of genes related to pro-tumoral processes such as adhesion or migration (NCAM1), proliferation (CDK1, TOP2A) or extensively described tumor markers (CDKN2A, MTOR), among others, while showing an impairment in immune-related functions." (PMID 35329826, 2022). "Prompt TOP2A transcription level mainly depends on tumor type." (PMID 35033076, 2022). "At present, the association between TOP2A expression and tumor-immune cell infiltration has not been fully reported." (PMID 35873470, 2022). "Interestingly, CNAs of TOP2A have a tumor subtype-specific role in contributing to gene expression variability." (PMID 36352434, 2022). "Moreover, the expression of TOP2A in HCC was higher than that of non-tumor tissues according to the ONCOMINE database." (PMID 35069905, 2022). "Thus, CPX down-regulated TOP2A expression and TOP2A knockdown further enhanced CPX anti-tumor effects, suggesting that at least part of the CPX effects on LUAD were mediated by TOP2A." (PMID 35251970, 2022). "Taken together, these data suggested that TOP2A may play a key role in promoting multiple oncogenic properties in MB and the upregulation of TOP2A in MB may contribute to tumor progression." (PMID 35912241, 2022). "Therefore, TOP2A, NCAPG, and BUB1B are possible prognostic indicators associated with tumor-infiltrating immune cells in the tumor microenvironment." (PMID 36245843, 2022).
tumor (continued). "First, analyze the mRNA expression of TOP2A in different tumor tissues." (PMID 35033076, 2022). "In this study, we did demonstrate the overexpression of TOP2A in most tumor types." (PMID 35778520, 2022). "The normal-like subtype consisted of eight tumours and showed a scattered expression of hub genes (except TOP2A), drug-target genes and somatically mutated genes without any pattern, perhaps an indication that tissue analysed was mixed with normal tissue." (PMID 36345011, 2022). "Moreover, we also investigated the correlation between TOP2A and above six immune checkpoints to provide more potential options for tumor therapy." (PMID 35778520, 2022). "Our study findings indicated that TOP2A may be a potential prognosis indicator and a target to reverse the immunosuppressive tumor microenvironment of SCLC." (PMID 35784467, 2022). "Besides, the positive association between the infiltration level of M2 macrophages and TOP2A expression in GBM hints a possibility that high TOP2A expression stimulates M2 macrophages’ tumor-promoting function in GBM." (PMID 35778520, 2022). "Above all, to achieve a better chemotherapy effect and prevent tumour recurrence, the TOP2A, RRM1, HER2 and ERCC1 mRNA or protein expression levels in NMIBC tissues could be detected after NMIBC." (PMID 35711974, 2022). "TOP2A is a nuclear enzyme that controls and alters the topologic states of DNA during transcription and mitosis, facilitating gene expression and mitotic progression, respectively, in tumor cells." (PMID 35109908, 2022). "Next, we identified candidate herbs and their effective components that may have an inhibitory impact on tumor progression via three hub genes (TOP2A, NUF2, and CCNB2)." (PMID 33946043, 2021). "Wong (2009) observed that high expression of TOP2A predicted microvascular invasion and advanced-stage tumor histology, which may indicate the early stage of HCC occurrence." (PMID 34939898, 2021). "YB-1 overexpression results in downstream TOP2A overexpression and tumor progression." (PMID 34638362, 2021). "Risk scores were correlated with tumor stage; BMF was associated with age, gender, grade, and stage; PPP2R5B and LGALS3 were correlated with stage; SQSTM1 was associated with age and gender; while TOP2A was correlated with grade and stage." (PMID 33712023, 2021). "Based on this inference, we screened three key miRNAs (hsa-miR-10b-3p, hsa-miR-23b-3p, and hsa-miR-139-3p) targeting four hub mRNAs (CCNB2, KIF18B, PLK1, and TOP2A) using the correlation analysis, survival analysis, expression analyses in stage, distant metastasis, tumor, and normal tissues." (PMID 33869028, 2021). "Then we investigate the potential function of TOP2A in tumor progression and metastasis." (PMID 32201520, 2020). "For TOP2A, Fisher's exact tests were significant in 4 of 40 tumor types for drug sensitivity." (PMID 31479512, 2020). "Further investigations may also lead to the development of tumor cell/biopsy evaluation of TOP2α isoforms as biomarkers for drug resistance, prognosis, and/or guide TOP2α-targeted therapies." (PMID 32566920, 2020). "For TOP2A, the Fisher's exact test was significant in 10 of 40 tumor types." (PMID 31479512, 2020). "However, in a study of 24,262 patients with diverse tumour types, only 4% of tumours had TOP2A amplification." (PMID 32024004, 2020). "This was predicted because ETO is a TOP2α poison, which is well known to inhibit tumor cell growth." (PMID 33334021, 2020). "Based on these results, therefore, we hypothesized that abnormal expression of TOP2A could be a positive tumor metastasis marker and a poor biomarker for prognosis." (PMID 32555395, 2020). "Furthermore, TOP2A overexpression is a positive tumor metastasis marker and a poor biomarker for prognosis." (PMID 31105744, 2019).
tumor (continued). "Moreover, we also found that the high TOP2A expression predicted poor overall survival compared with the low TOP2A expression in HCC patients with tumor stage 2 (log-rank P = 0.0073) and tumor stage 3 (log-rank P = 0.00066)." (PMID 31886163, 2019). "Besides, topoisomerase-1 and 2A gene copy numbers are elevated in patients mismatch repair-proficient tumor samples, suggesting that TOP2A is required to deal with high replication stress." (PMID 31266445, 2019). "Previous studies also suggested that high TOP2A expression levels could indicate tumor aggressiveness and poor outcome." (PMID 31216997, 2019). "Another critical interactor of TOP2A is the tumor suppressor and DNA repair gene BRCA1." (PMID 31083655, 2019). "The TOP2A showed a totally nuclear expression pattern, and it was almost negative in all normal urothelium that could be studied adjacent to tumor tissue." (PMID 31216997, 2019). "We also found that TOPO1 and TOP2A expression levels were lower in RAS-mutated tumours, an association not previously reported in the literature, and that reinforces differences in the biology of these tumours." (PMID 31537838, 2019). "Higher TOP2A expression in NSCLC predicts more malignant biological behavior of the tumor, and more importantly TOP2A has been widely used as an independent prognostic factor in NSCLC and high expression of TOP2A is associated with worse prognoses of NSCLC patients." (PMID 30369945, 2018). "Moreover, we detected the relationship between miR-144-3p and TOP2A in mice tumor tissues by Real Time PCR analyses." (PMID 30544723, 2018). "IF analysis using TOP2A antibody also showed strong expression of TOP2A in the four tumor types." (PMID 29352201, 2018). "Since TOP2A protein represents the ultimate expression of TOP2A as well as tumor cell proliferation, therefore, detection of the protein may be better correlated with the tumor biology and predict the clinical outcome more precisely than genetic analysis." (PMID 29587760, 2018). "In addition, Kaplan-Meier analysis revealed that patients with high TOP2A expression (We defined the relative expression > 7 as high expression) clearly had poorer tumor-free survival and overall survival rates." (PMID 30544723, 2018). "There was not a statistically significant association of TOP2A expression with clinical parameters, such as age, gender or pathological tumor stage." (PMID 28355294, 2017). "Western blotting assay were used to measure the expression of ERCC1/TOP2A in tumor tissues." (PMID 27895586, 2016). "TOP2A was downregulated in resistant tumor samples in contrast to sensitive samples." (PMID 26824188, 2016). "In addition, TOP2A gene deletion (TOP2A/CEP17 ratio ≤0.8) concurrently with HER2 gene deletion (HER2/CEP17 ratio ≤0.8) was observed in 10% (2/20) of tumor tissues." (PMID 25695068, 2015). "Therefore, the association between ERCC1, TYMS, RRM1, TUBB3 and TOP2A expression levels with the pathogenesis and development of ESCC was investigated using a clustered analysis in terms of tumor invasion and lymphatic and distal metastasis." (PMID 24926347, 2014). "Although this seems counterintuitive considering recurrent tumors express higher levels of TOP2A, we propose that TOP2A only marks the proliferative state of tumor bulk while a small minority of TOP2A-negative, slow-cycling cells preserve more stemness capacity and tumor reinitiating capability." (PMID 25237769, 2014). "On the other hand, DRZ has been recently reported to deplete TOP2A from tumor cells." (PMID 25406834, 2014). "TOP2A is one of cellular topoisomerases that determines tumor cell response to chemotherapeutics." (PMID 24103454, 2013).
tumor (continued). "Our results also confirmed the predictive role of TOP2A gene in tumor chemo-sensitivity." (PMID 24216996, 2013). "Orange signals for TOP2A gene and green signals for centromeric region of chromosome 17 were observed; however, no numerical alterations in TOP2A gene and chromosome 17 were noticed in any tumor sample." (PMID 23398928, 2013). "Therefore, microsatellite analysis was performed in all tumor specimens using six couples of primers targeting the 17q21 amplicon, containing TOP2A and ERBB2 genes, and 3p24 and 20q12–q13.1 loci, containing respectively TOP2B and TOP1 genes." (PMID 24216996, 2013). "For these reasons, TOP2A expression is a double-edged sword: on one side, high TOP2A levels could indicate tumor aggressiveness and poor outcome, on the other side, this could determine a positive response to chemotherapeutic drugs targeting this enzyme." (PMID 23928695, 2013). "Furthermore, the absolute relation between the presence of TOP2A in tumors of patients with biochemical recurrence is an evidence that this protein is related to late stages of tumor development." (PMID 23398928, 2013). "TOP2A gene amplification occurred independently of tumor grade." (PMID 22240029, 2012). "Furthermore, the HER2 gene is located on chromosome 17q21-22, close to TOP2A, resulting in 33–60% of HER2-positive tumours containing concurrent modifications of TOP2A." (PMID 22333602, 2012). "In this regard we tested whether the TOP2A/β-tubulin combination index was related to tumor response after adjusting for standard clinical pathological variables." (PMID 22578285, 2012). "In addition high expression of TOP2α has been profilied as an indicator of tumor aggressiveness and poor outcome in several tumor types." (PMID 22300273, 2012). "We hypothesized that such target based expression indices would provide a biologically comprehensive measurement of either TOP2A or β-tubulin activity in a patient’s tumor, and thus its likely dependence on either of these targets." (PMID 22578285, 2012). "TOP2A is a key enzyme in regulating various chromosomal events during tumor cell replication." (PMID 21785684, 2011). "Notably, while E2F1, Ki-67 and TOP2A transcript levels areall cell-cycle regulated, we generally observed E2F1 immunostaining in a largerproportion of tumor cells, in contrast to Ki-67 and TOP2A, which stained only aminority fraction of cells." (PMID 21629784, 2011). "Although no clear correlations between the expression level and patient outcome were observed here, the genes TOP2A, ETV4 and BIRC5 are interesting candidate targets for the 17q gain associated with poor outcome, but further validation is required on a larger tumor set." (PMID 18522746, 2008). "In addition, TOP2A plays a carcinogenic role in a variety of tumor types." (PMID 41284119, 2025). "Notably, integrating TOP2A inhibitors into platinum-based regimens has shown promise in enhancing chemosensitivity and mitigating resistance in recurrent OC, while TOP2A quantification in both tumor and stromal compartments serves as a prognostic biomarker for treatment outcomes." (PMID 41235254, 2025). "Moreover, EZH2 and TOP2A are highly co-expressed in HCC tumor tissues, clinically." (PMID 40271060, 2025). "The ‘tumor cells 1’ cluster had the gene expression characteristic of stem-like tumor cells with an elevated expression of genes involved in cell division and chromosome segregation such as Top2a, Mki67, Cenpf, Cenpe, Incenp, Anln, Ccna2, Kif20b, Ccnb1, and Smc4." (PMID 39769061, 2024).